CHMP1A (charged multivesicular body protein 1A)
Diseases named in the same sentence as CHMP1A in open-access papers:
CHMP1A is named in the same sentence as 46 diseases in open-access papers, as found by Europe PMC text mining. Sharing a sentence is not in itself a finding about the gene and the disease. The quoted sentences say what the papers report.
pancreatic cancer (6 papers, 2009 to 2025). "This suggests that ATRA-induced growth inhibition in human pancreatic cancer cells is mediated, at least in part, via Chmp1A." (PMID 39850424, 2025). "In current study, we found the two commonly identified proteins, CHMP1A and CHMP1B, were tumor-associated proteins in the Pancreatic Cancer Database." (PMID 36266629, 2022). "In the same study, authors also examined the expression of CHMP1A in human pancreatic tumors by immunochemical labeling of human pancreatic tumor TMAs, including 10 cases of pancreatic ductal carcinoma (PDACs)." (PMID 36266629, 2022). "They found variable expressional patterns of CHMP1A in human pancreatic tumors, including a prominent expression of CHMP1A in PDACs." (PMID 36266629, 2022). "We additionally reported that Chromatin modifying protein 1A (Chmp1A) of the Endosomal sorting complex required for transport (ESCRT) family member plays a role in pancreatic cancer as a tumor suppressor." (PMID 29463243, 2018). "Collectively our data provides evidence that Chmp1A mediates the growth inhibitory activity of ATRA in human pancreatic cancer cells via regulation of CRBP-1." (PMID 19216755, 2009). "We examined the involvement of Chmp1A in ATRA signaling by determining the effect of ATRA on Chmp1A expression in pancreatic tumor cell lines." (PMID 19216755, 2009). "We recently have shown that Charged multivesicular protein/Chromatin modifying protein1A (Chmp1A) functions as a tumor suppressor in human pancreatic tumor cells." (PMID 19216755, 2009). "In addition to their transporting/sorting function, a tumor suppression role of CHMP1A in kidney and pancreatic cancers has also been suggested." (PMID 36266629, 2022). "The objective of our study was to investigate whether Chmp1A is involved in ATRA-mediated growth inhibition of human pancreatic tumor cells." (PMID 19216755, 2009). "Chmp1A mRNA and protein was reduced and/or altered (protein) in various human pancreatic tumors." (PMID 19216755, 2009). "We then investigated whether Chmp1A is mechanistically involved in the growth inhibitory action of AA, 5-FU or GEM in pancreatic cancer cells." (PMID 29463243, 2018). "The objective of our study was to investigate whether Chmp1A expression and/or localization is essential for ATRA mediated growth inhibition of human pancreatic tumor cells." (PMID 19216755, 2009). "Since our microarray data indicates a potential involvement of Chmp1A in ATRA signaling, we tested this hypothesis by treating pancreatic tumor cells with ATRA in vitro." (PMID 19216755, 2009). "It is also the first report demonstrating the sufficient, but not required function of Chmp1A in the mediation of anticancer action of 5-FU and GEM in pancreatic cancer." (PMID 29463243, 2018).
microcephaly (5 papers, 2018 to 2024). A congenital or acquired developmental disorder in which the circumference of the head is smaller than normal for the person's age and sex. "Several conflicting potential mechanisms have been proposed to explain why loss-of-function (LOF) mutations in an ESCRT-III member, CHMP1A, cause microcephaly with pontocerebellar hypoplasia and short stature in humans." (PMID 30044992, 2018). "We recently showed human loss-of-function (LOF) mutations in ESCRT-III member CHMP1A cause autosomal recessive microcephaly with pontocerebellar hypoplasia, but its mechanism was unclear." (PMID 30044992, 2018). "Previous studies have not only found that loss-of-function mutations in human CHMP1A lead to reduced cerebellar size (pontocerebellar hypoplasia) and cerebral cortex size (microcephaly), but also identified CHMP1A as a new candidate gene for late-onset PD." (PMID 35893077, 2022). "This deficit is twice as large as the reduction in mitotic progenitors in the developing cortex and matches human CHMP1A null patients, whose cerebellar hypoplasia is strikingly severe in relation to more modest microcephaly." (PMID 30044992, 2018). "Altogether, the reduced body size, microcephaly, reduced basal ganglia, and cerebellar hypoplasia in Chmp1a null mice closely model the phenotype of CHMP1A null patients." (PMID 30044992, 2018). "PCH8 is characterized by dystonia, ataxia, microcephalus, and non-degenerative, non-progressive cerebellar hypoplasia and is associated with mutations in the CHMP1A gene." (PMID 38347586, 2024). "In addition, both impaired progenitor maintenance in CHMP1A null organoids and microcephaly in Chmp1a null mice can be partially rescued by downstream Shh signaling activation either chemically or genetically." (PMID 30044992, 2018).
pontocerebellar hypoplasia type 8 (3 papers, 2018 to 2023). "CHMP1A is causal for pontocerebellar hypoplasia type 8, an autosomal recessive neurodevelopmental disorder." (PMID 29723191, 2018). "Pontocerebellar hypoplasia type 8(PCH8) is a rare neurodegenerative disorder, reportedly caused by pathogenic variants of the CHMP1A in autosomal recessive inheritance, and CHMP1A variants have also been implicated in other diseases, and yet none of the prenatal fetal features were reported in PCH8." (PMID 37789895, 2023).
Intellectual disability (2 papers, 2020 to 2024). "Interestingly, VPS4A is known to directly interact in humans with an intellectual disability gene, CHMP1A, from nuclear magnetic resonance, affinity chromatography, pull down and two hybrid assays, and both are part of the necroptosis and endocytosis pathways." (PMID 32005800, 2020).
asthma (1 paper, 2025). "The asthma locus 16q24.3 near CHMP1A was also associated with CRSsNP (ORCRSsNP = 1.068 [1.043–1.094])." (PMID 41213931, 2025).
autism spectrum disorder (1 paper, 2023). A spectrum of developmental disorders that includes autism, and Asperger syndrome. "Other nine variants reported in CHMP1A are associated with neurological and developmental disorders, including three missense variants linked to autism spectrum disorder, and six missense variants associated with late-onset Parkinson’s disease." (PMID 37789895, 2023).
diabetes mellitus (1 paper, 2015). A metabolic disorder characterized by abnormally high blood sugar levels due to diminished production of insulin or insulin resistance/desensitization. "The charged multivesicular body protein 1A (CHMP1A) gene located in the vicinity of the 5-th most significant signal in the scan for allele frequency difference is a particularly interesting candidate gene that has been implicated in diabetes mellitus." (PMID 25970163, 2015).
metastatic tumors (1 paper, 2024). "CHMP1A, B2M, and RSU1 loss alterations were significantly enriched in RB1-loss primary tumors at a frequency of 7%–18% above RB1-WT primary tumors and were significantly enriched in RB1-loss metastatic tumors at a frequency of 16%–23% above RB1-loss primary tumors." (PMID 38751776, 2024).
osteoarthritis (1 paper, 2022). A noninflammatory degenerative joint disease occurring chiefly in older persons, characterized by degeneration of the articular cartilage, hypertrophy of bone at the margins and changes in the synovial membrane. "For seven genes (ALDH1A2, CHMP1A, CRADD, FAM53A, LTBP1, RPP25, and TGFA), we found evidence that GWAS signals for osteoarthritis colocalize with mQTLs in these genes and are additionally associated with gene expression levels in the same tissue." (PMID 35679866, 2022). "We found such an eQTL effect below nominal significance levels for five genes in low-grade osteoarthritis cartilage (ALDH1A2, CHMP1A, FAM53A, RPP25, and TGFA), two genes in high-grade osteoarthritis cartilage (FAM53A and LTBP1), and one gene in synovium (CRADD)." (PMID 35679866, 2022).
renal carcinoma (1 paper, 2018). A carcinoma arising from the epithelium of the renal parenchyma or the renal pelvis. "CHMP1A (charged multivesicular body protein 1A) is known to act as a tumor suppressor in pancreatic and renal cancer by inhibition of tumor cell proliferation." (PMID 30259648, 2018).
renal cell carcinoma (1 paper, 2023). "CHMP1A had been reported as a tumor suppressor in renal cell cancer via proliferation inhibition." (PMID 36759883, 2023).
type 2 diabetes (1 paper, 2015). "Their results indicated that the aberrant DNA methylation pattern of CHMP1A gene might result in the disorders of epigenetic modules specific to type 2 diabetes." (PMID 25970163, 2015).
Ureteral obstruction (1 paper, 2021). Obstruction of the flow of urine through the ureter. "When Chmp1a+/− littermates were subjected to unilateral ureteral obstruction, Chmp1a+/− mice also showed markedly increased injury compared to controls." (PMID 34426578, 2021).
tumor (10 papers, 2009 to 2023). "Taken together, the tumor suppressor function of CHMP1A in cancers has been demonstrated in cell lines and animal models, also linked to the aberrant isoform of Chmp1a." (PMID 36266629, 2022). "However, an up‐regulation of CHMP1A in HNSCC might also have a converse effect as multifunctional roles were shown for several tumor‐associated genes." (PMID 30259648, 2018). "In our study, we used fresh frozen PDAC tumor tissue and identified CHMP1A protein to be up-regulated in PDACs in the comparison with NAT." (PMID 36266629, 2022). "Overall, Hrs (ESCRT-0) and Tsg101 (ESCRT-I) seem to be mostly up- and Vps37A (ESCRT-I), Chmp1A and Vps4B mostly down-regulated in tumor samples." (PMID 24641493, 2014). "In contrast, silencing of Chmp1A in PanC-1 cells resulted in the elevation of cell and xenograft tumor growth." (PMID 19216755, 2009). "Stable over-expression of Chmp1A in PanC-1 cells resulted in cell growth inhibition and tumor xenograft inhibition, respectively." (PMID 19216755, 2009). "The overexpression of NLS-deleted Chmp1A could promote the tumor cell growth, whereas, overexpression of C-terminal deleted Chmp1A could inhibit tumor growth." (PMID 36266629, 2022). "We have recently shown that Chmp1A is a novel tumor suppressor, especially in the pancreas." (PMID 19216755, 2009). "CHMP1A has two protein-coding transcript isoforms, according to NCBI annotation; transcript variant 1 contains 6 exons encoding a 240 residue protein, and transcript variant 2 contains 7 exons encoding a 196 residue protein, which functions as a tumor suppressor in human kidney and pancreas." (PMID 23273016, 2012). "Chmp1A and CADM2, belonging to cell adhesion molecules family, had been found to be a tumor suppressor gene in RCC." (PMID 32038722, 2019). "Reduction of another ESCRT-III subunit, Chmp1A, by shRNA enhanced the tumorigenic potential by increasing anchorage-independent growth in HEK 293T cells and led to tumor formation in a xenograft assay in athymic mice." (PMID 24641493, 2014). "However, the tumor suppressor role of CHMP1A in human cancer is still not well-studied, yet." (PMID 36266629, 2022).
cancer (6 papers, 2013 to 2023). A tumor composed of atypical neoplastic, often pleomorphic cells that invade other tissues. "This is the first data to show a molecular link between Chmp1A and the anti- cancer action of 5-FU or GEM." (PMID 29463243, 2018). "Chmp1A, an ESCRT protein, inhibits cancer cell proliferation, invasion and signaling activity via MVB formation, highlighting the potential role of SCAMP3 during cancer development." (PMID 33493138, 2021). "The overexpression of Chmp1A and CADM2 significantly suppressed cancer growth and invasion." (PMID 32038722, 2019). "Importantly, a number of studies have shown changes in expression of ESCRT components in human cancer cells, including changes in expression of ESCRT-I components Tsg101 and Vps37A and ESCRT-III components Chmp1A and CHMP3." (PMID 23418496, 2013).
kidney disease (6 papers, 2021 to 2025). "In recent genome-wide association studies for kidney disease, Dpep1 and Chmp1a, were identified as key regulators of ferroptosis." (PMID 36090053, 2022). "Our analysis prioritized both DPEP1 and CHMP1A as kidney disease risk genes in kidney proximal tubules, likely mediating the effect of the eGFR GWAS signal observed on chromosome 16." (PMID 34426578, 2021). "Collectively, these results suggest a kidney-specific mQTL/eQTL effect of rs164748, which prioritized both DPEP1 and CHMP1A as kidney disease risk genes." (PMID 34426578, 2021). "Here we identified DPEP1 and CHMP1A as kidney disease genes via the triangulation of genome-wide association studies, human kidney mQTL and eQTL data." (PMID 34426578, 2021). "Cellular studies indicate that CHMP1A is an important regulator of programmed death through a single pathway and leads to the development of kidney disease by altered cellular iron trafficking." (PMID 36589680, 2022). "Cellular studies indicate that both Dpep1 and Chmp1a are important regulators of a single pathway, ferroptosis and lead to kidney disease development via altering cellular iron trafficking." (PMID 34426578, 2021). "Dpep1 and Chmp1a levels also strongly and negatively correlated in mouse models of kidney disease induced by UUO, FA, APOL1, and PGC1a." (PMID 34426578, 2021). "Treatment of Chmp1a heterozygous mice with liproxstatin offered marked protection from kidney disease, indicating the key role of ferroptosis in Chmp1a-mediated tubule injury in vivo." (PMID 34426578, 2021). "Here, the authors investigate a kidney disease GWAS locus with functional genomics data, CRISPR editing and mouse experiments to identify DPEP1 and CHMP1A as putative kidney disease genes via ferroptosis." (PMID 34426578, 2021). "To determine whether the second GWAS prioritized gene, CHMP1A, also plays a role in kidney disease development, we next imported Chmp1a mutant mice." (PMID 34426578, 2021). "In summary, these data indicate the protective role of Chmp1a in kidney disease." (PMID 34426578, 2021). "We identify DPEP1 and CHMP1A as kidney disease genes and important regulators of ferroptosis." (PMID 34426578, 2021). "Our studies indicate that pharmacological targeting of ferroptosis through Dpep1 or Chmp1a in kidney tubule cells could offer therapeutic benefits for patients with kidney disease." (PMID 34426578, 2021). "Here we identify two kidney disease genes Dipeptidase 1 (DPEP1) and Charged Multivesicular Body Protein 1 A (CHMP1A) via the triangulation of kidney function GWAS, human kidney expression, and methylation quantitative trait loci." (PMID 34426578, 2021).
infection (3 papers, 2018 to 2024). The state of being infected such as from the introduction of a foreign agent such as serum, vaccine, antigenic substance or organism. "After infection with WT M. tuberculosis, 85.2% of bacilli were associated with CHMP1A staining, which appeared in a punctate pattern adjacent to the bacilli." (PMID 30482832, 2018).
CHMP1A also shares sentences with these, for which no sentence is quoted: genetic disease (2 papers); acute myeloid leukaemia (1); Ataxia (1); atrial septal defect (1); bone marrow failure (1); breast carcinoma (1); cardiovascular disorder (1); colorectal cancer (1); Crohn disease (1); cutaneous melanoma (1); Dystonia (1); Fanconi anaemia (1); hydrocephaly (1); Hypertonia (1); Hypotonia (1); late-onset Parkinson disease (1); neurodevelopmental disorder (1); neurological diseases (1); non-melanoma skin carcinoma (1); Nystagmus (1); oculocutaneous albinism (1); pancreatic ductal carcinoma (1); Patent ductus arteriosus (1); Patent foramen ovale (1); Pigmentary retinopathy (1); pontocerebellar hypoplasia (1); ptosis (1); schizophrenia (1); Sepsis (1).